NLRP3 (NLR family pyrin domain containing 3)
Diseases named in the same sentence as NLRP3 in open-access papers (continued):
Sharing a sentence is not in itself a finding about the gene and the disease.
tumor (continued). "Furthermore, the surface adhesin Fap2 of F. nucleatum can induce the secretion of pro-inflammatory cytokines IL-8 and C-X-C motif chemokine ligand 1 (CXCL1) and NOD-like receptor family pyrin domain containing 3 (NLRP3) activation to promote tumor migration and invasion." (PMID 39966840, 2025). "Thus, sustained NLRP3 activation could foster an inflammatory microenvironment conducive to tumor progression." (PMID 39744485, 2025). "In addition, NLRP3 inflammasome can modulate the recruitment and polarization of TAMs and myeloid-derived suppressor cells (MDSCs), which secrete proinflammatory mediators that support tumor progression." (PMID 41560727, 2025). "This duality positions NLRP3 as a therapeutic target, where inhibition could attenuate pro-tumorigenic signaling in inflammation-driven cancers or enhance pyroptosis in malignancies where inflammasome activation is tumor suppressive." (PMID 40564985, 2025). "Although NLRP3 inhibitors have worked to reduce inflammation, their combination with other therapeutic methods, such as immune checkpoint inhibitors, such as anti-PD-1, may enhance their anti-tumor effects by modulating the TME." (PMID 40141358, 2025). "Immunohistochemistry (IHC) and Western blot analyses of NLRP3‐overexpressing xenografts revealed elevated intratumoural levels of pyroptosis‐associated markers (Cleaved caspase‐1 and cleaved GSDMD) relative to control tumours after sustained drug administration." (PMID 38804602, 2024). "Therefore, siRNA-based gene silencing strategies may serve as an effective targeted therapy for NLRP3 inflammasome in order to reduce inflammation and to facilitate the anti-tumor drugs effects." (PMID 39433537, 2024). "There have been no studies to assess whether disrupting NLRP3 related pathways can cause tumour regression in OC." (PMID 39516433, 2024). "Similarly, TAMs can promote the release of ATP, and the rise in ATP concentration in the TME binds to tumour cell P2X7 receptors and opens cell surface K+ channels, which in turn promotes the activation of NLRP3 inflammatory vesicles and induces tumour cell pyroptosis." (PMID 38652105, 2024). "Therefore, the effect of CB on HCC depends on whether oncogenic or tumor-suppressive mechanisms are mainly activated through the NLRP3 inflammasome." (PMID 39544286, 2024). "In addition, NLRP3 has been reported to be aberrantly upregulated in various tumor tissues, especially in the highly invasive subtype, indicating that the NLRP3 inflammasome may be associated with cancer progression, prognosis, and response to treatment." (PMID 39144184, 2024). "Similarly, HMBG1 has been reported as another DAMP involved in NLRP3 mediated tumour progression." (PMID 39516433, 2024). "It was also proven that NLRP3 could promote tumor growth and metastasis in OSCC." (PMID 38392321, 2024). "Interestingly, both NLRP3 agonists and inhibitors have shown anti-tumor efficacy." (PMID 39318624, 2024). "Therefore, the development of NLRP3 inflammasome and pyroptosis-derived therapeutic strategies using chemotherapy drugs or non-coding RNA molecules is necessary due to anti-apoptotic nature of tumor cells." (PMID 39433537, 2024). "NLRP3 may exert different functions depending on the tissue-specific characteristics at the site of metastasis and the original tumor, as well as the different stages of tumor development." (PMID 38523155, 2024). "Thus, the NLRP3 inflammasome is crucial for an effective anti-tumor immune response." (PMID 39456655, 2024). "Additionally, the C3a secreted from the tumors could also engage with C3aR1 in the tumor microenvironment to promote NLRP3 inflammation-induced metastasis." (PMID 38894892, 2024). "Moreover, the pro-tumor effect of miR-233 might be intertwined with its capability to inhibit NLRP3 inflammasome activation." (PMID 38001342, 2024).
tumor (continued). "Five cases of normal testicular tissue adjacent to a tumor (testis removed due to tumorous growth) and five cases of atrophied cryptorchid testicular tissue (testis removed) were analyzed for immunohistochemistry to determine NLRP3 expression in cryptorchid tissue." (PMID 39840312, 2024). "However, MCC950 not only alleviates the symptoms of EAE, but also inhibits tumor development, indicating that it may have potential use for the treatment of NLRP3 inflammasome-related cancer." (PMID 37497237, 2023). "In addition, our study suggests that 17β-estradiol may be effective in HCC treatment as it can inhibit tumor cell growth and proliferation by activating the NLRP3 inflammasome and the caspase-1-dependent pyroptosis in HCC cells." (PMID 36763290, 2023). "P2RX7 can be considered to be a fine tuner of the tumor microenvironment, given that it is able to induce cell proliferation and death as well as to modulate the immune response through various pathways, notably through the release of IL-18 following the activation of the NLRP3 inflammasome." (PMID 37298187, 2023). "NLRP3 may also influence tumor responses by interfering with the efficacy of immunotherapy." (PMID 37715239, 2023). "Furthermore, NLRP3 inflammasome may also influence the anti-tumor immune response in LCE patients, as IL-1β can enhance the recruitment and activation of natural killer cells and cytotoxic T cells, which can eliminate tumor cells." (PMID 37715239, 2023). "Other researchers have proposed an anti-tumor vaccine based on a proton-driven deformable nano-delivery system, which not only efficiently delivers antigen peptides into the cytoplasm of immune cells, but also enhances the innate immune system by acting as an adjuvant to activate the NLRP3." (PMID 37497237, 2023). "Also, LPS, which is a tumor antigen, induces the formation of lung tumors upon NLRP3 activation." (PMID 37893079, 2023). "Furthermore, NLRP3 inflammasome is mainly expressed in immune cells, and high Sorcin expression might inhibit the tumoricidal activity of immune cells against tumor cells and the protective effect of NLRP3 inflammasome against HCC." (PMID 37833249, 2023). "Besides, BRCC3 could activate NLRP3 inflammasome-dependent pyroptosis, which could then promote tumor progression." (PMID 37564930, 2023). "However, some studies have found that NLRP3 can suppress the growth of certain tumor types." (PMID 37885032, 2023). "Recent studies have indicated that miR-340 functions as a tumor suppressor and cell cycle regulator and that miR-340 could affect pyroptosis through NLRP3 inflammasome and the TLR4/NF-kB signaling pathway, subsequently leading to decreased inflammatory signaling." (PMID 36834660, 2023). "Pharmacological inhibition of NLRP3 inflammasome in HNSCC mouse models significantly reduces the IL-1β production, which reduces MDSCs, regulatory T cells (Tregs) and tumor-associated macrophages (TAMs) but increases CD4 and CD8 T cells in tumors to improve anti-tumor immunity." (PMID 36742298, 2023). "Functionally, the activation of the NLRP3 inflammasome can result in the pyroptotic programmed death of cells and the release of the proinflammatory cytokines IL-1β and IL-18, which can establish inflammatory microenvironmental conditions conducive to tumor growth." (PMID 37885032, 2023). "Similarly, NLRP3 is overexpressed in tissues of head and neck squamous cell carcinoma resulting in increased IL-1β concentration in blood, spleen, draining lymph nodes, and tumor tissues." (PMID 36932407, 2023). "Additionally, it has been found that another chemotherapy drug, cisplatin, can activate NLRP3 in tumor cells, and targeting NLRP3 may overcome chemoresistance." (PMID 38116060, 2023). "This suggests that targeting NLRP3 may be a potential way of augmenting anti-tumor immunity." (PMID 37705746, 2023).
tumor (continued). "TAMs are a subset of tumor-infiltrating macrophages that sustain the abnormal growth of neoplastic cells, which, together with CAFs, are capable of inducing the activation of the canonical NLRP3 inflammasome and secreting pro-inflammatory cytokines, feeding the tumor." (PMID 37891577, 2023). "This study confirmed that lack of NLRP3 inflammasome is involved in HCC progression and 17β-estradiol-induced activation of NLRP3 inflammasome may be effective in HCC treatment as it inhibited tumor cell growth and proliferation by triggering CASP1-dependent pyroptosis in HCC cells." (PMID 36763290, 2023). "Additionally, NLRP3 inflammasome activation can suppress the anti-tumor immune response by inducing the polarization of macrophages toward an M2 phenotype, which can secrete immunosuppressive cytokines such as IL-10 and TGF-β, and inhibit the function of T cells and natural killer cells." (PMID 37715239, 2023). "However, when NLRP3 or IL-1β is silenced, the tumor-promoting effect is impaired." (PMID 37497237, 2023). "Also, an increased expression of NLRP3 inflammasome‐related genes in CM tumor samples was associated with low or no response to immune checkpoint therapy." (PMID 36707938, 2023). "Furthermore, NLRP1/NLRP3 may be involved in macrophage polarization, T-cell exhaustion, Tregs, immune checkpoint regulation, and other tumor immune regulatory processes." (PMID 36541912, 2022). "Consequently, inhibition of IL-1 by anakinra or canakinumab or of the NLRP3 inflammasome might prevent cancer development or have therapeutic efficacy at the beginning of tumor development, as demonstrated by the CANTOS trial." (PMID 36293159, 2022). "Therefore, in this study, we analyzed the correlations between NLRP1/NLRP3 and prognosis in patients with GC using experimental data and public databases, such as Oncomine, Tumor Immune Estimate Resource (TIMER), The Cancer Genome Atlas (TCGA), and Kaplan-Meier Plotter." (PMID 36541912, 2022). "NLRP1 and NLRP3 might be involved in the same tumor immune-related pathways." (PMID 36541912, 2022). "Therefore, NLRP1/NLRP3 may regulate immune infiltration in GC through these immune- and tumor-related pathways." (PMID 36541912, 2022). "In addition, NLRP3 inflammasome might have an aggravating effect on tumor cell proliferation and metastasis." (PMID 35890097, 2022). "In addition, NLRP1/NLRP3 may also be involved in several important tumor-related pathways, such as MAPK and JAK-STAT pathways." (PMID 36541912, 2022). "Thus, we asked whether Nlrp3-/- animals present alterations of BM progenitors during tumor growth, which may affect the generation of MDSC subsets." (PMID 36032139, 2022). "We hypothesized that the increase in ROS caused by luteolin is not the main pathway of NLRP3 activation and that ROS production occurs due to the ’damage caused by the drug to tumour cell mitochondria." (PMID 36105214, 2022). "Moreover, G-MDSCs from Nlrp3-/- mice not only downregulated Lox1 and Pdl1 expression, which are associated with G-MDSC identity and tumor immune evasion, respectively, but also demonstrated enrichment in type I IFN signatures, which is linked to re-programming of granulocytic cells in the TME." (PMID 36032139, 2022). "In addition, tumor dying cells release large amounts of ATP, which mediate NLRP3 activation." (PMID 36032139, 2022). "Interestingly, CD11c–CD11b+Gr1+ MDSCs frequencies were comparable between WT and Nlrp3-/- mice, whereas assessment of MDSC subsets revealed an increased accumulation of CD11bhighLy6C+Ly6G– M-MDSCs and markedly decreased levels of CD11bhighLy6C–Ly6G+ G-MDSCs into the tumor site of Nlrp3-/- mice." (PMID 36032139, 2022). "Importantly, pharmacologic MCC950-mediated inflammasome inhibition resulted in a significant increase in the spleen M-MDSCs and subsequent reduction of G-MDSCs as compared to the control-treated group, recapitulating the results obtained in Nlrp3-/- tumor-inoculated animals." (PMID 36032139, 2022).
tumor (continued). "The NLRP3 inflammasome increased the recruitment of CD11b+Ly6ChighLy6G− myeloid cells into tumors, and IL-1β increased the recruitment of the granulocytic fraction (CD11b+Ly6G+Ly6Clow) in the primary tumor and the monocytic fraction (CD11b+Ly6ChighLy6G−) in metastatic tumors." (PMID 35739593, 2022). "Additionally, NLRP3 activation reduced the tumor cell growth in both cells lines, whereas suppressing NLRP3 could result in tumor cell line specific growing pattern." (PMID 36517518, 2022). "Despite NLRP3 ablation having no impact on gastric tumorigenesis in gp130F/F mice, it remained possible that NLRP3 may contribute to a subset of tumor-associated cellular processes in the gastric compartment." (PMID 35299732, 2022). "Moreover, the inflammatory environment and related substances that are ubiquitous in the tumour environment, such as ATP released after cell death, can easily activate the NLRP3 inflammasome pathway and cleave gasdermin D (GSDMD) by activating caspase-1 and cause tumour-cell pyroptosis." (PMID 35289335, 2022). "All immune cell clusters were identified in both the tumor and juxtatumor samples, but the relative proportions of mmDC, pDC, B cells, Plasma cells, Neutrophils, and Mast cells were increased in the tumor samples whereas MMAC_PDL1 and MMAC_NLRP3 were increased in the juxtatumor sample." (PMID 35418195, 2022). "Therefore, NLRP3 is expected as a novel target for tumor and microenvironment regulation." (PMID 34955826, 2021). "Therefore, NLRP3 is also considered as a new type of tumor therapeutic target." (PMID 34955826, 2021). "Importantly, direct exposure of NLRP3 activating alum crystals or of the NLRP3 inhibitor as well as of blocking antibodies directed against CXCR2 or of the CXCR4 inhibitor did not significantly change the proliferation of SCC VII or 4T1 tumor cells in vitro." (PMID 34876407, 2021). "Since inflammation promotes tumor metastasis and can be triggered by activating the NLRP3 inflammasome via ROS-dependent mitochondrial damage, the silibinin-induced mitochondrial fission inhibits NLRP3 inflammasome activation and migration possibly by an antioxidant mechanism." (PMID 34733852, 2021). "Similarly, a synergistic action with the tumor drug paclitaxel on A549 cells was exerted by activation of the ASK1/p38 MAPK signaling pathway and, consequently, of the thioredoxin-interacting protein (TXNIP)-associated NLRP3 inflammasome (TXNIP-NLRP3)." (PMID 33435246, 2021). "Therefore, a series of additional signaling studies was conducted to further define a link between CD8+ T cell activation and NLRP3 inflammasome activation in tumors, revealing tumor PD-L1-mediated triggering of NLRP3 activation via a STAT3-protein kinase R (PKR) pathway." (PMID 34638239, 2021). "We have also proven that NLRP3 could promote tumor growth and metastasis in OSCC." (PMID 34454534, 2021). "Thus, our data uncovered a novel mechanism that DDP induced pyroptosis via activation of MEG3/NLRP3/caspase-1/GSDMD pathway in TNBC to exert anti-tumor effects, which may help to develop new strategies for the therapeutic interventions in TNBC." (PMID 34326697, 2021). "In addition, neutrophilia in 4T1 tumor-bearing mice was abrogated on NLRP3 inflammasome inhibition." (PMID 34876407, 2021). "Finally, In in vivo experiment, the suppression of NLRP3 knockdown impaired tumor growth of PCa." (PMID 34930938, 2021). "Thus, NLRP3 expression levels may vary between different tumors or stages of tumor development and NLRP3 may exert various effects via different mechanisms." (PMID 32435622, 2020). "Indeed, NLRP3 appeared to be a good candidate as this receptor is well-described to sense DAMPs, such as ATP or uric acid released by necrotic cells, and since necrosis of tumor cells is frequent during cancer progression." (PMID 33042810, 2020).
tumor (continued). "Therefore, the priming of IFN‐γ‐producing CD8+ T cells by dying tumor cells fails in the absence of a functional IL‐1 receptor 1 and in Nlrp3‐deficient or caspase‐1‐deficient mice unless exogenous IL‐1β is provided." (PMID 33179413, 2020). "However, the effect of NLRP3 complex formation on tumor progression remains controversial." (PMID 33613529, 2020). "Moreover, NLRP3 levels were low in RCC tumor samples, and that it might function as a tumor suppressor in RCC31." (PMID 32303673, 2020). "Besides, LXRα could promote the tumor metastasis by down-regulating the NLRP3 inflammasome in ccRCC." (PMID 30770793, 2019). "Here we expand these observations and demonstrate that the NLRP3 inflammasome pathway, which regulates the maturation and secretion of IL-1β is activated in CAFs in response to tissue damage, implicating a mechanism by which CAFs mediate tumour-promoting inflammation." (PMID 31558756, 2019). "However, the role of Sp-1 in activation of the NLRP3 inflammasome in CRC tumor tissues and monocytes remains largely unknown." (PMID 31118894, 2019). "It was noticeable that e-As4S4 eliminated NLRP3 inflammasomes significantly in tumor tissue, indicating that e-As4S4 could change the inflammatory microenvironment to some extents in the tumor tissue." (PMID 31106156, 2019). "Therefore, the effect of targeting NLRP3 expression with miRNAs in tumors and immune cells may vary depending on tumor and/or cell type." (PMID 31118894, 2019). "In addition, we revealed that the NLRP3 inflammasome might function as a tumor suppressor in ccRCC according to the wound healing, transwell migration and invasion assays." (PMID 30770793, 2019). "Therefore, we investigated whether the inhibition of NACHT, LRR and PYD domains-containing protein 3 (NLRP3) inflammasome in macrophages regulated the metastatic potential of tumor cells." (PMID 31439870, 2019). "Moreover, our data suggest that the mechanism by which CAF-derived NLRP3/IL-1β facilitate tumour growth and metastasis is by altering the immune cell milieu towards a tumour-tolerating phenotype, and by enhancing endothelial cell adhesiveness and cancer cell invasiveness." (PMID 31558756, 2019). "NLRP3 deletion significantly suppressed the tumor incidence, mean tumor count and tumor size of visible tumors on the surface of lungs induced by B(a)p or B(a)p plus LPS, implying NLRP3 inflammasome may be involved in the enhancement of pulmonary inflammation in lung tumorigenesis." (PMID 30696442, 2019). "Thus, in-depth understanding the expression and function of NLRP3 inflammasome may offer new insights into tumor therapy." (PMID 29716544, 2018). "Moreover, chemotherapeutic agents may have an effect on the NLRP3 inflammasome of cells existed in the tumor microenvironment." (PMID 29716544, 2018). "Moreover, silencing NLRP3 expression significantly inhibited OSCC tumor growth in vivo." (PMID 29716544, 2018). "Thus, while long-term chronic inflammation may constitute a mechanism to support the growth of several tumors, the acute and robust activation of NLRP3 may have the capacity to activate the immune system for tumor destruction." (PMID 30619282, 2018). "Thus, we hypothesized that XLOC_000647 might play a tumor suppressor role by negative regulation of NLRP3 expression." (PMID 29386037, 2018). "Given that blockade of NLRP3 inflammasome could delay tumorigenesis in SCCHN mice by reducing the production of IL-1β, and the stimulation on NLRP3 inflammasome from early tumor is less than advanced tumor, which might account for the decreased expression of NLRP3 and pro-Caspase-1." (PMID 28865486, 2017). "However, our findings suggest that the stimulation of over-expressed P2X7R on HNSCC or epithelial cells produces active IL-1β via the NLRP3 inflammasome pathway independent of the surrounding tumor-associated macrophages." (PMID 28430665, 2017).